NDUFC2-KCTD14 (NDUFC2-KCTD14 readthrough)
Description:
Accessory subunit of the mitochondrial membrane respiratory chain NADH dehydrogenase (Complex I), that is believed not to be involved in catalysis. Complex I functions in the transfer of electrons from NADH to the respiratory chain. The immediate electron acceptor for the enzyme is believed to be ubiquinone (By similarity).
Tractability: Antibody: UniProt predicts a signal peptide or a membrane-spanning region.
Gene: Protein-coding gene on chromosome 11 (78,016,971 to 78,079,865, reverse strand). Ensembl gene ENSG00000259112.
Subcellular location: Mitochondrion inner membrane
Subcellular location (Human Protein Atlas): Mitochondria
Gene Ontology:
Biological process: mitochondrial electron transport, NADH to ubiquinone
Cellular component: mitochondrion; respiratory chain complex I; mitochondrial inner membrane
Genetic constraint (gnomAD): Loss-of-function variants: 4 observed, 8.43 expected, observed/expected ratio (o/e) 0.47, 90% interval 0.23 to 1.09. That is too few expected variants to judge how well the gene tolerates losing a copy. Missense variants: 156 observed, 151.27 expected, observed/expected ratio (o/e) 1.03, 90% interval 0.9 to 1.18. Synonymous variants: 61 observed, 55.54 expected, observed/expected ratio (o/e) 1.1, 90% interval 0.89 to 1.36.